BCL2 (BCL2 apoptosis regulator)
Diseases named in the same sentence as BCL2 in open-access papers (continued):
Sharing a sentence is not in itself a finding about the gene and the disease.
ischemia (continued). "Substantial evidence indicates that CREB plays critical roles in the neuronal responses to ischemia, such that activation and overexpression of CREB significantly reduces ischemia-mediated brain injury and increases BDNF and Bcl-2 expression." (PMID 32566081, 2020). "Given the protective effects of nesfatin-1 against ischemia, we investigated the effects of nesfatin-1 administration on several GFAP-positive cells and apoptotic-related proteins (Bax/Bcl-2), following transient global cerebral ischemia-reperfusion." (PMID 32284834, 2019). "The effects of post-ischemia treatment with Ast IV on the expression of HIF-1α, iNOS, Bcl2, and Caspase3 were abolished by 2-MeOE2 (vs. SIR+Ast IV group, P<0.01)." (PMID 25238237, 2014). "miR-15a is a target of PPAR- transrepression directly regulates BCL-2 and contributes to PPAR-mediated vascular protection against ischemia-like insults.67miR‐15a regulates oxygen-glucose deprivation/reperfusion (OGD/R)‐induced neuronal injury by targeting BDNF." (PMID 40190672, 2024). "The myocardial protection of adenosine A2a receptor after ischemia may involve the cAMP-PKA signaling pathway and the interaction of Bcl-2-Beclin-1." (PMID 35571159, 2022). "Post-ischemia treatment with Ast IV significantly increased HIF-1α, iNOS, and Bcl2 protein expression, to 4.36±0.20-fold, 4.11±0.14-fold, and 4.14±0.17-fold of the control, respectively, whereas Caspase3 expression decreased to 0.45±0.087-fold that of the control (vs. SIR group, P<0.01)." (PMID 25238237, 2014). "Neither ischemia nor hemin administration modified the basal expression of Bcl-2 protein, a well-known suppressor of apoptosis." (PMID 23592614, 2013). "qPCR analysis performed at the early phase after ischemia revealed a time dependent decrease in Bax, Bak, and Bcl-xL and no alteration in Bcl-2 mRNA expression in response to retinal ischemia." (PMID 19862336, 2009). "The most prominent finding of this study is that the σ receptor agonist, afobazole, rescues microglia, but not neurons, from ischemia-induced cell death by regulating the expression of the pro-apoptotic proteins, Bax and caspase-3, and the anti-apoptotic protein Bcl-2." (PMID 31156357, 2019). "Moreover, afobazole preserved Bcl-2 expression in microglia, but not neurons following exposure to 24 h ischemia." (PMID 31156357, 2019). "Incubation of HA14–1 with ischemia-damaged SSM in the absence of calcium leads to loss of cytochrome c from mitochondria, indicating that functional inhibition of bcl-2 in the absence of calcium increases the selective permeation of the outer membrane (MOMP) during reperfusion." (PMID 25756500, 2015). "However, in our data, p38 MAPK activated antiapoptosis genes Bcl-2 and Bcl-XL, and promoted cell survival, which could explain that p38 MAPK protects retinal cells from ischemia injury." (PMID 22876136, 2012). "In vitro, a decrease in the expression of Bcl-2 has been reported in cultured retinal cells stimulated by various means, including simulated ischemia and excitotoxicity, whereas no obvious change in Bcl-2 gene expression was observed in vivo in retinas where ischemia was induced by increased IOP." (PMID 19862336, 2009). "Thus, afobazole failed to significantly blunt the reduction in Bcl-2 produced by ischemia." (PMID 31156357, 2019). "Thus, the decreased bcl-2 content in combination with additional calcium overload stress and oxidative damage may sensitize the MPTP opening in mitochondria following reperfusion compared to mitochondria following ischemia alone." (PMID 25756500, 2015).
ischemia (continued). "Compared with the sham group, p38 and caspase-3 expressions in the frontal cortex were increased at different time points of ischemia in the MCAO model group, while no significant changes were found in NF-кB, Bax, or Bcl-2 expression." (PMID 31611791, 2019). "Before the onset of simulated ischemia, mRNA expression of the anti-apoptotic factors BCL-XL and BAG1 was similar in preconditioned and non-preconditioned CB-MSCs, whereas BCL-2 expression was suppressed by HP (relative expression: 1.6±0.1×10−4 vs. non-HP 3.6±0.3×10−4; P < 0.01)." (PMID 26380983, 2015). "A few cells in vehicle-treated stroke rats also expressed Bcl-2 and MAP2 double-labeling, indicating that ischemia alone, without any treatment intervention, might slightly induce the expression of Bcl-2 in neurons." (PMID 19807907, 2009). "The target/reference (BCL-2/GAPDH) mean ratio was 0.58 ± 0.16 for control group and 1.14 ± 0.13 for treatment group.Therefore, this study was undertaken to reveal the effect of the pentoxifylline on BCL-2 gene expression changes in kidney after a period of ischemia or lack of oxygen in rats." (PMID 24734070, 2014).
acute lymphoblastic leukemia (89 papers, 2012 to 2026). Leukemia with an acute onset, characterized by the presence of lymphoblasts in the bone marrow and the peripheral blood. "TYK2 point mutations found in T-ALL (T-cell acute lymphoblastic leukemia) cell lines exhibited transformation potential via the STAT1/BCL2 pathway." (PMID 35042970, 2022). "Elevated expression of S100A8/S100A9 caused glucocorticoid resistance in MLL rearranged infant acute lymphoid leukemia and negatively associated with BCL2 inhibitor venetoclax in AML." (PMID 34485305, 2021). "Elevated expression of miRNAs encoded from hsa-mir-15a~16–1~3613 locus has been associated with glucocorticoid resistance in acute lymphoblastic leukemia, whereas mir-15 deletion has been linked to overexpression of apoptotic gene BCL2 in cancer." (PMID 33995896, 2021). "By inducing pre-apoptotic BCL-2 proteins, including BAX proteins, GC exacerbates the expression of the anti-apoptotic BCL-2 protein by causing caspase cascade and inducing apoptosis in the cell line of lymphoblastic leukaemia." (PMID 32102534, 2020). "Furthermore, another direct target of miR-34 is BCL2, which has been correlated with lower survival and high risk features in acute lymphoblastic leukemia." (PMID 34837933, 2021). "In acute lymphoblastic leukemia (ALL), gal-9 induced apoptosis in ALL cells in a concentration-dependent manner through mechanisms associated with Bax/Bcl-2 expression and caspase-3 activation." (PMID 39539619, 2024). "Overexpression of anti-apoptotic protein BCL-2 and hypermethylation are hallmarks of acute lymphoblastic leukemia (ALL) and can be pharmacologically addressed by venetoclax (VEN) and hypomethylating agents (HMA) such as azacytidine (AZA) or decitabine (DEC)." (PMID 42309255, 2026). "BAFF and its receptors up-regulating pro-survival (Bcl-2, Bcl-xL) as well as growth-promoting (c-Myc) proteins while down-regulating pro-apoptotic Bax in both Hodgkin lymphoma cells and acute lymphoblastic leukemia." (PMID 39941037, 2025). "Bcl-2 was first discovered in acute lymphoblastic leukemia and has been shown to play a cytoprotective role against apoptosis, making it an apoptosis-inhibitory protein." (PMID 37762259, 2023). "B-cell lymphoma-2 (BCL2) has been identified in acute lymphoblastic leukaemia and has later been shown to inhibit apoptosis, while BCL2-associated X (BAX) is a well-known proapoptotic factor." (PMID 37525208, 2023). "MLL::AF4 acute lymphoblastic leukemia (ALL) showed a highly expressed BCL‐2 that is directly regulated by MLL::AF4." (PMID 36819153, 2023). "Our analysis also gave BCL2 inhibitors associated with SF1126 or sirolimus (both MTOR inhibitors), and this combination of BCL2 with MTOR inhibitors is used in resistant acute lymphoblastic leukemia." (PMID 34864885, 2022). "In line with this, targeting Bcl-2 and mTOR concurrently (e.g., with everolimus, temsirolimus) was shown to synergize against Bcl-2-antagonist-resistant B-cell lines and primary acute lymphoblastic leukemia cells by down-regulation of Mcl-1." (PMID 34572784, 2021). "This study defined to probe the apoptotic effect of sub-toxic dose of prednisolone on the expression and level of promoter methylation of BAX and BCL2 genes in CCRF-CEM acute lymphoblastic leukemia cells." (PMID 32102534, 2020). "The aim of the current research was defined to probe the effect of sub-toxic prednisolone dose on the level of promoter methylation and gene expression of BAX and BCL2 in the T acute lymphoblastic leukemia cell line (CCRF-CEM)." (PMID 32102534, 2020). "Research indicates that Bcl2 was discovered in acute lymphocytic leukemia and was later proven to protect cells from programmed cell death." (PMID 33144550, 2020). "In acute lymphocytic leukemia, circPVT1 can upregulate the expression of c-Myc and anti-apoptotic Bcl-2 proteins." (PMID 31309249, 2019).
acute lymphoblastic leukemia (continued). "These mutations include the BCR-ABL fusion event, associated with chronic myeloid leukemia (CML) and acute lymphoblastic leukemia (ALL), and the BCL2-IGH and IGH-cMyc fusion events, associated with follicular non-Hodgkin lymphoma." (PMID 29300727, 2018). "We tested the apoptotic sensitivity of BCR-ABL-expressing B-lineage acute lymphoblastic leukemia cell lines engineered to depend on Bcl-2, Bcl-xL, Mcl-1 or Bfl-1 overexpression for survival." (PMID 28594323, 2017). "Similarly, CI-1040 has been shown to induce dexamethasone lethality in acute lymphoblastic leukemia cells through the pro-apoptotic molecule BCL-2 and MEK/ERK signaling pathway." (PMID 36135081, 2022). "In addition, VTX is known to exhibit a higher level of sensitivity to the T‐cell acute lymphoblastic leukemia cell lines in correspondence with a higher expression level of Bcl‐2 proteins." (PMID 34173723, 2022). "Knockdown of MYB sensitized acute lymphoblastic leukemia (ALL) cells to doxorubicin and 6-mercaptopurine by downregulating anti-apoptotic BCL2." (PMID 40725394, 2025). "The combination of the third‐generation BCR–ABL1 inhibitor olverembatinib with the Bcl‐2 inhibitor venetoclax has shown high efficacy in relapsed Ph+ acute lymphoblastic leukemia (ALL) patients." (PMID 39184861, 2024). "The expression of the anti-apoptotic protein BCL2 has been shown to be deregulated in T-cell acute lymphoblastic leukemia (T-ALL), where different T-ALL cells display a differential response to the BCL2-specific inhibitor venetoclax." (PMID 36902436, 2023). "Some studies have shown that overexpression of BCL-2 or BCL-xL is commonly observed in acute lymphoblastic leukemia (ALL) and chronic lymphocytic leukemia (CLL)." (PMID 34603598, 2021). "The selectivity and potency of S55746 was firstly evaluated in the well-described BCL-2-dependent acute lymphoblastic leukemia (ALL) RS4;11 cell line, which express high levels of BCL-2 but low levels of BCL-XL." (PMID 29732004, 2018). "Caspase-dependent apoptosis by ONC201 has been observed in acute lymphoblastic leukemia (ALL) via modulation of Bcl-2 and IAP-family proteins." (PMID 27602582, 2016). "Our data have also implications for lymphoblastic leukemia therapy and may explain why repressing either Bcl-2 expression (e.g., by an Bcl-2 inhibitor) or Notch function (e.g., by γ-secretase inhibitors) may individually be sufficient for sensitizing the cancerous cells to GC-induced apoptosis." (PMID 22319533, 2012). "AZD4320, a dual BCL-2 and BCL-XL inhibitor, and AZD5991, which targets MCL-1, induce cell death in acute lymphoblastic leukemia cells when combined." (PMID 40662801, 2025). "In contrast to AML, there is less evidence regarding the impact of overexpression of apoptosis-related proteins in acute lymphoblastic leukemia (ALL), especially BCL-2, where expression levels exhibit higher variability." (PMID 38338698, 2024). "It was also reported that R98S mutation in RPL10 associated with pediatric T-cell acute lymphoblastic leukemia (T-ALL) generates specialized ribosomes that increase IRES-dependent translation of antiapoptotic factor BCL-2 thereby increasing leukemic cell survival." (PMID 36806717, 2023). "Despite this combination raising the levels of anti-apoptotic Bcl-2, it downregulated expression of c-Myc and hTERT, showing ZME as a potential adjuvant for treatment of pre-B-acute lymphoblastic leukemia." (PMID 36980962, 2023). "Based on preclinical evidence of dependence on BCL2 and BCL-XL, several small series have investigated the use of BH3-mimetics in acute lymphoblastic leukemia/lymphoma (ALL)." (PMID 35659041, 2022). "GC induces activation of caspase cascade and induces apoptosis in the cell line of lymphoblastic leukemia by increasing in BAX protein and decreasing the BCL2 protein." (PMID 32102534, 2020).
acute lymphoblastic leukemia (continued). "In terms of lymphocytic leukemia, knockdown of circPVT1 accelerated the apoptosis of acute lymphocytic leukemia (ALL) cells by declining the expression of c-Myc and Bcl-2." (PMID 33069241, 2020). "A subsequent study identified an oncogenic TYK2-STAT1 pathway in T-cell acute lymphoblastic leukemia (T-ALL) cell lines, mediated through gain-of-function TYK2 mutations or activation of IL10 receptor signaling, that leads to the upregulation of BCL2 and T-ALL cell survival." (PMID 26654227, 2015). "Recently, it is found out that Bcl-2 is the therapeutic target of miR-17-92 cluster in BCR-ABL positive Acute Lymphoblastic Leukemia (ALL) and overexpression of miR-221/222 downregulate Bcl-2 and induce apoptosis in gastrointestinal stromal tumors." (PMID 26551008, 2015). "In acute lymphoblastic leukemia, curcumin (15 μM) enhanced the apoptotic effects induced by imatinib (1 μM) on SUP-B15 cells through the downregulation of the Akt/mTOR pathway and the upregulation of the Bax/Bcl-2 ratio." (PMID 34299604, 2021). "Studies on peripheral blood and bone marrow specimens from paediatric patients with acute lymphoblastic leukaemia (ALL) demonstrated that following Berlin‐Frankfurt‐Munster (BFM) chemotherapy, an elevation in miR‐125b and down‐regulation of Bcl‐2 correlate with short leukaemia‐free survival." (PMID 33332677, 2021). "In contrast to our previous studies of ABT-737-resistance in acute lymphoblastic leukemia cell lines, we found no changes in BCL-2 level between parental and ABT199-R cells." (PMID 25590803, 2015). "In addition, the suppression of MYB in acute lymphoblastic leukemia (ALL) cells transfected with doxycycline-regulated lentiviral sh-c-Myb sensitized these cells to treatment with DNA-targeting drugs (doxorubicin and the antimetabolite 6-mercaptopurine) by downregulation of anti-apoptotic BCL2." (PMID 38835346, 2024). "However, BCL2 inhibition, alone or in combination regiment with BCR-ABL1 inhibitor, did not reduce the self-renewal of primitive leukemic cells, while strongly induced cell death on primary Ph+ Acute Lymphoblastic Leukemia (ALL)." (PMID 34884309, 2021). "In another study, performed with acute lymphoblastic leukemia (ALL) and AML patients-derived cell lines, the sublines resistant to BCL-2 inhibitors (ABT-737 and its orally active analog ABT-263—navitoclax) or MDM2 antagonist SAR405838 were developed." (PMID 31331108, 2019). "Moreover, previous study showed that adipocytes protected acute lymphoblastic leukaemia (ALL) cells from vincristine, a chemotherapeutic agent, by sequestering lipophilic vincristine, as well as upregulating anti-apoptotic proteins, Pim-2 and Bcl-2." (PMID 31334678, 2019). "Here, we investigated the activity of the BCL-2 inhibitor venetoclax (VEN, ABT-199) in B-cell precursor acute lymphoblastic leukemia and found heterogeneous sensitivities in BCP-ALL cell lines and in a series of patient-derived primografts." (PMID 31358732, 2019). "Genetic and pharmacologic inhibition of STAT5 activity decreases expression of apoptosis inhibitors MCL1 and BCL2 and inhibits leukemogenesis of BCR-ABL1+ acute lymphoblastic leukemia (ALL), both in cell lines and newly diagnosed and relapsed/TKI-resistant ALL patients." (PMID 31684144, 2019). "The NUP214-ABL1 fusion kinase, which is frequently observed in acute lymphoblastic leukemia (ALL), has a vital function in facilitating the cooperative attachment of TLX1 and STAT5 to enhancers, thus triggering the activation of significant oncogenes such as MYC and BCL2." (PMID 39838405, 2025). "Although T-cell acute lymphoblastic leukemia (T-ALL) is similar in many ways to CLL and AML, it has not responded well to venetoclax or navitoclax BH3 mimetics, presumably because it expresses active pro-survival proteins other than BCL-2, BCL-XL, and BCL-W." (PMID 30008477, 2019).